NF1 (neurofibromin 1)
Diseases named in the same sentence as NF1 in open-access papers (continued):
Sharing a sentence is not in itself a finding about the gene and the disease.
autosomal dominant disease (35 papers, 2008 to 2025). Autosomal dominant form of disease. "NF1 is an autosomal dominant disease, and about 50% of the children with NF1 inherit a pathogenic gene variant from their parents." (PMID 40895107, 2025). "NF1 is an autosomal dominant disease that affects around 1:3000 people and is characterized by loss of function mutations in the neurofibromin gene (NF1)." (PMID 38543265, 2024). "Neurofibromatosis type I (NF1) is a common inherited autosomal-dominant disease that affects 1 in 3500 individuals with mutations that promote the loss of function of the NF1 protein, neurofibromin, which is involved in diverse signaling cascades." (PMID 35887183, 2022). "NF1 is an autosomal dominant disease caused by inheritance of one mutated copy of the NF1 gene located on chromosome 17q11.2." (PMID 34680266, 2021). "NF1 is an autosomal dominant disease caused by a mutation in the NF1 gene in the long arm of chromosome 17 (17q11.2); it has an incidence of approximately 1 in 3000 people." (PMID 34581917, 2021). "Neurofibromatosis 1 (NF1) is a rare autosomal dominant disease that causes the dysregulated growth of Schwann cells." (PMID 34727946, 2021). "Neurofibromatosis type 1 (NF1) (MIM#162200) is an autosomal dominant disease caused by haploinsufficiency of the NF1 gene (MIM #613113)." (PMID 30843352, 2019). "NF1 is an autosomal dominant disease due to deletions or mutations of the neurofibromin gene located on chromosome 17p11.2." (PMID 27493794, 2016). "NF is an autosomal dominant disease caused in humans by deficiencies in one of the neurofibromin genes, NF1 or NF2." (PMID 25940629, 2015). "Neurofibromatosis 1 (NF1) is an autosomal dominant disease caused by heterozygous mutations of the NF1 gene." (PMID 23984171, 2013). "NF-1 is an autosomal dominant disease caused by mutation of a gene on the long arm of chromosome 17, which encodes a protein known as neurofibromin, a negative regulator of Ras oncogene." (PMID 20531996, 2009). "The NF1/von Recklinghausen neurofibromatosis, caused by germ line mutations of the NF1 tumor suppressor gene, is one of the most common autosomal dominant inherited disorders, occurring at a frequency of one in every 4,000 individuals." (PMID 18522746, 2008). "NF1 is an autosomal dominant disease caused by mutations in the NF1 gene located at chromosome 17." (PMID 37301968, 2023). "Neurofibromatosis type 1 (NF1), also called von Recklinghausen disease, is an autosomal dominant disease caused by mutations in the NF1 gene encoding neurofibromin that occurs in approximately 1 in 3000 people with 100% penetrance, but highly variable expressivity." (PMID 36335228, 2022). "This autosomal dominant disease is caused by mutations of the NF1 gene located at chromosome 17q11.2, which encodes the neurofibromin, a protein involved in the regulation of several cellular signaling pathways and responsible for cell proliferation and differentiation." (PMID 31416195, 2019). "Neurofibromatosis 1 (NF1) is a rare autosomal dominant disease characterized by increased Schwann cell proliferation in peripheral nerves." (PMID 35248131, 2022). "NF1 is an autosomal dominant disease leading to multisystem disorders." (PMID 36246612, 2022). "NF is an autosomal dominant disease with two distinct forms, NF1 and NF2." (PMID 25295078, 2014).
CNS tumors (28 papers, 2015 to 2026). "With established clinical activity in NF1-associated CNS tumors and a favorable oral dosing profile, mirdametinib represents a promising candidate for expanding MEK-directed strategies in neuro-oncology." (PMID 41514664, 2026). "Together, these data reveal the existence of an HCN channel-dependent mechanism for Nf1-mutant CNS tumor-associated neuronal midkine production." (PMID 35589737, 2022). "Patients with NF1 mutations appear susceptible to ALT+ CNS tumors with poor prognosis." (PMID 34069193, 2021). "Although direct RAS mutations are rare in primary CNS tumors, alterations in RAS signaling, such as NF-1 loss and aberrant receptor tyrosine kinase activation, contribute to malignant progression." (PMID 40362343, 2025). "Out of 12 patients with CNS tumors, positive results (Tier IA/IB) were found in 2 patients (1 men, 1 women), one of which had mutations in the IDH1 gene and the other in the NF1 gene." (PMID 39338229, 2024). "Conversely, the clinical monitoring and treatment strategies for NF1-derived CNS tumors are still in the process of optimization." (PMID 38281032, 2024). "More recently, in 2021, the fifth edition of the WHO classification of tumors of the CNS has introduced atypical neurofibromatous neoplasms of uncertain biological potential (ANNUBP) in the setting of NF1." (PMID 39061237, 2024). "The most common CNS tumor is optic pathway glioma (OPG), which is also a hallmark and diagnostic criteria of NF1." (PMID 32486389, 2020). "In contrast, CNS tumors in adults with NF1 tend to be of higher histological grade and have a worse prognosis than those occurring in children." (PMID 32486389, 2020). "While direct RAS mutations are not very frequent, RAS-related signaling pathways are frequently activated in certain CNS tumors such as GBM, through alternative mechanisms like EGFR amplification, NF1 loss, and PDGFR overexpression, which converge on the RAS/RAF/MEK/ERK and PI3K/AKT axes." (PMID 40362343, 2025). "NF1 showed the highest prevalence (n = 8; 1% of cases); the majority of patients having CNS tumors." (PMID 33674644, 2021). "OPGs are the most common CNS neoplasms in NF-1, encountered in 15% of NF-1 patients." (PMID 31655505, 2019). "Aberrant activation of the MAPK pathway is a hallmark of several CNS tumors, frequently driven by genetic alterations such as point mutations, gene fusions, amplifications, or overexpression, most commonly involving RTKs, RAS, RAF, and regulators of the pathway such as SHP2 and NF1." (PMID 41514664, 2026). "However, only two of 44 patients with a CNS tumor carried a germline variant (TSC2, NF1), and none of these two patients had a 1st–3rd-degree family member with a CNS tumor." (PMID 33332384, 2020).
vasculopathy (21 papers, 2011 to 2026). "This highlights the importance of recognizing NF1-related vasculopathy as a potential cause of delayed vascular complications." (PMID 39906425, 2025). "NF-1, which affects 1 in 3000–5000 individuals, is associated with reduced life expectancy due to malignancies and vascular diseases, including NF-1 vasculopathy." (PMID 39849241, 2025). "The pathogenesis of vasculopathy in NF1 is not fully understood, but it is thought to be linked to the role of neurofibromin in blood vessels." (PMID 38790247, 2024). "Young age, a dosage of more than 50 Gy to the circle of Willis, NF-1, and previous surgery were additional known risk factors for the development of moyamoya as one of the most common vasculopathy in these patients." (PMID 36230704, 2022). "It is now avoided in NF1-related LGGs, due to the known risk of secondary malignancies and radiation-induced vasculopathies." (PMID 32486389, 2020). "NF-1 vasculopathy may lead to vascular fragility, an increased risk of bleeding during invasive procedures, and difficulty in achieving hemostasis." (PMID 39849241, 2025). "Although the frequency of NF-1 vasculopathy is unknown, vasculopathy is the second most common cause of mortality in patients with NF-1, after malignancy." (PMID 34090195, 2021). "NF-1-related vasculopathy may be associated with vascular fragility, and the endovascular approach might be preferable." (PMID 34090195, 2021). "NF-1 is occurs in 1 in 3,000 individuals and has been associated with vasculopathy." (PMID 27867667, 2016). "Additionally, these patients should be carefully followed, taking into account that vasculopathy associated with NF-1 may lead to a fatal outcome." (PMID 24200148, 2013). "The presence of unexplained swelling, hemorrhage, or pulsatile masses in such individuals should prompt the consideration of NF1-related vasculopathy, including aneurysmal changes and pseudoaneurysm formation." (PMID 39906425, 2025). "This case highlights the importance of considering NF-1 vasculopathy in patients with abdominal bleeding and adopting tailored strategies to address its challenges." (PMID 39849241, 2025). "Although pulmonary vascular involvement has been documented in NF1, NF1-related vasculopathy typically involves systemic vessels such as the aorta and renal, mesenteric, or coronary arteries." (PMID 41487738, 2025). "Vasculopathy in patients with NF-1 is rare, with a reported incidence of 2.3%–3.6%.2,4) However, because most NF-1 lesions are clinically silent, this is probably an underestimate." (PMID 34239644, 2021). "It is reported that vasculopathy is over seven times more likely to occur in patients with NF-1 under 30 years compared to their unaffected peers." (PMID 32733046, 2020). "This also applies to vasculopathy and other NF1-related features, including café-au-lait spots or tibial pseudarthrosis, in which the somatic second hit has been detected in the pathologic tissue." (PMID 31730495, 2019). "The precise mechanisms involved in NF1, the pathogenesis of vasculopathy are poorly understood but are likely related to the function of neurofibromin, the protein product of the NF1 gene." (PMID 24952383, 2014). "NF-1 vasculopathy of the cerebrum, endocrine system, gastrointestinal tract and heart have also been reported." (PMID 24200148, 2013). "Thus, germline and lineage-restricted Nf1 heterozygous mice represent a tractable platform for understanding NF1 vasculopathy." (PMID 34934133, 2021). "Deaths related to vasculopathy or second tumors are much less frequent and do not appear to be systematically linked to NF1 status and/or radiotherapy." (PMID 26098902, 2015).
nervous system tumors (18 papers, 2012 to 2026). "It is caused by the development of tumors in the nervous system, resulting from mutations in the NF1 gene located on chromosome 17q11.2." (PMID 41788126, 2026). "Neurofibromatosis type 1 (NF1) results from germline mutations in the tumor-suppressor gene NF1 and predisposes patients to developing nervous system tumors." (PMID 37520682, 2023). "We next evaluated the PK and PD of several MEK inhibitors that have shown promise in patients with NF1-associated nervous system tumors." (PMID 33669386, 2021). "Considering the susceptibility of NF1-related nervous system tumors at an early age, trametinib could suit a wider age range of the population since it is available as a suspended powder." (PMID 36015104, 2022). "NF1 is an autosomal dominant genetic syndrome caused by mutations in genes coding for neurofibromin, it is characterized by cutaneous manifestations as cafe-au-lait spots with a large number of nervous system tumors." (PMID 25879938, 2015). "There is one ongoing phase II trial investigating the benefit of trametinib for treating LGGs and pNFs in NF1 individuals, and other reports on trametinib for treating NF1-related nervous system tumors have also been published in recent years." (PMID 36015104, 2022).
adenocarcinoma (16 papers, 2016 to 2025). A common cancer characterized by the presence of malignant glandular cells. "In fact, adenocarcinomas associated with NF1 seem to be rare events and have been reported in only a few studies." (PMID 32425982, 2020). "Adenocarcinomas involving the whole gastrointestinal tract have been detected in patients with NF1 but the association is unclear." (PMID 30187267, 2018). "The adenocarcinoma I1 and carcinoid I2 components of the mixed neoplasm shared the same mutations in BRAF (p.Gly466Ala), NF1 (p.Pro1359LeufsTer19 and p.Glu1928Ter), STK11 (p.Gly188AlafsTer99), and AKT2 (p.Leu52Ter) genes." (PMID 34926584, 2021). "We observed a higher mutation frequency of NF1, ATR, and BRCA1 in EGFR-mutant SCC compared to EGFR-mutant adenocarcinoma." (PMID 34195081, 2021). "NF1 is a mutated tumor suppressor in both of the NSCLC subtypes, adenocarcinoma and squamous cell." (PMID 31867044, 2019). "Although TCGA group has identified NF1 to be substantially mutated in adenocarcinomas, there was none identified in our patients." (PMID 26992220, 2016). "In this report, the patient was diagnosed with multiple tumors (GIST, NET of the minor ampulla, and adenocarcinoma of the major ampulla), of which GIST and NET are likely related to NF1, a diagnosis confirmed by germline genetic testing." (PMID 32425982, 2020).
neurodevelopmental disorder (13 papers, 2013 to 2025). A behavioral and cognitive disorder with onset during the developmental period that involves impaired or aberrant development of intellectual, motor, or social functions. "Given that cognitive and motor impairments are often co-morbidities in children with NF1, our findings suggest that this transient ‘MEKi in milk’ protocol can serve as a common prevention strategy for multiple NF1-associated neurodevelopmental disorders." (PMID 25535838, 2014). "The cerebellum plays a critical role in motor control, cognition, and social interaction, suggesting that cerebellar defects likely contribute to NF1-associated neurodevelopmental disorders." (PMID 25535838, 2014). "Neurodevelopmental disorders such as NF1 often involve complex alterations in cellular signaling and complex pathophysiology." (PMID 32697780, 2020). "This is a 4-year-old patient of Italian ancestry, with a negative family history for NF1 and neurodevelopmental disorders." (PMID 40225171, 2023). "Moreover, the absence of a significant PAF-age correlation in the NF1 group is consistent with previous research in other neurodevelopmental disorders that has reported the absence of a relationship between PAF and age." (PMID 37608248, 2023).
gastrointestinal tumors (10 papers, 2011 to 2024). "A gastrointestinal tumor should be considered if individuals with NF1 mutations suffer gastrointestinal symptoms." (PMID 37773168, 2023). "If there occur gastrointestinal symptoms in the patients with NF1 mutation, the possibility of a gastrointestinal tumor should be suspected." (PMID 36620543, 2022). "Although there are many reports on gastrointestinal tumors associated with NF1, there are few cases of appendiceal tumors." (PMID 34581917, 2021). "Furthermore, our case highlights one challenge inherent in the diagnosis of gastrointestinal tumors associated with NF-1." (PMID 39403336, 2024). "In the case of co-existing GIST and other GI tumors, which mostly arise in the upper GI tract, second NF1 somatic mutations might play a significant role." (PMID 21838856, 2011). "Moreover, mutations in NF1 were also observed in other digestive system tumors." (PMID 37147639, 2023). "While cutaneous neurofibromas typically remain benign, they are often complicated by gastrointestinal tumors several years after the diagnosis of NF1." (PMID 37773168, 2023). "In a recent study, a germline NF-1 nonsense mutation in exon 37 was detected by DNA sequence analysis, showing that the GI tumor arose through NF-1 gene inactivation." (PMID 22018031, 2011). "However, we could not find any other data on the risk of other GI tumors, including NETs, after mastectomy with NF1." (PMID 38282102, 2024). "Currently, there are no screening guidelines for gastrointestinal tumors in patients with NF-1, and surgery is the preferred treatment for GISTs and NETs in NF-1." (PMID 39403336, 2024). "Despite the lack of current screening guidelines for gastrointestinal tumors in patients with NF-1, early diagnosis and management play a crucial role in reducing both mortality and morbidity." (PMID 39403336, 2024). "While correlation does not necessarily imply causation, these findings suggested that the relationship between NF1 and YAP1 in NOZ cells may also occur in primary GBC tumors and could potentially be a common feature in gastrointestinal tumors." (PMID 37147639, 2023).
infection (7 papers, 2011 to 2024). The state of being infected such as from the introduction of a foreign agent such as serum, vaccine, antigenic substance or organism. "Thus, the expression of PKC δ in Nf1 deficient or proficient cells was examined after the co-infection of sc or shRNA-PKC α and β." (PMID 25301738, 2014). "Herein, we purified two new NF environmental isolates (NF45 and NF1) and tested their in vivo virulence using experimental infection in mice." (PMID 39735262, 2024). "To evaluate the potential for the environmental isolates NF1 and NF45 to cause disease, we utilized a mouse model of infection." (PMID 39735262, 2024). "Mouse infection with NF1 and NF45 revealed marked differences in symptom onset and disease severity that indicate these two newly isolated N. fowleri strains display distinct virulence phenotypes." (PMID 39735262, 2024). "Infections initiated with thesame amount of PYΔpy01365(NF1) orPYΔpy01365(NF2) resulted in a delay in host death as comparedto YM." (PMID 21625465, 2011). "In vivo experiments showed that NF1 displayed a slower progression of the infection from the olfactory into deeper brain regions, with fewer parasites invading the cerebrum at day 4 post infection." (PMID 39735262, 2024). "Previous studies have identified numerous host-cell transcription factors usurped by JCPyV during infection including cMyc, AP-1 (cJun and cFos), NFAT4, SMAD4, YB-1, NF-1, and others." (PMID 31561471, 2019). "It is clear that after the initial delay during the first few days ofthe infection PYΔpy01365(NF1) shows no erythrocyte restrictionand invades all erythrocytes with similar efficiency than YM." (PMID 21625465, 2011).
neurological diseases (6 papers, 2013 to 2024). "Last, NF1 is both a neurological disorder and a cancer predisposition syndrome." (PMID 38816530, 2024). "LZTR1 interacts with CUL3 and neurofibromin 1 (NF1) to regulate nighttime sleep by increasing GABA receptor signaling and has been associated with RAS-related neurological diseases caused by NF1 deficiency." (PMID 39062695, 2024). "GFAP, a marker of intermediate filaments in astrocytes that become hypertrophic in response to insult, has been shown to be increased in a number of neurological diseases, including NF1." (PMID 32074109, 2020). "As the level of neurofibromin is altered in CNS cells of patients with NF1, a host of CNS-specific impairments occur, requiring the need for multiple neurologically relevant antibodies to understand the complexities of this neurological disease in a swine model." (PMID 32074109, 2020).